CD4 (CD4 molecule)
Diseases named in the same sentence as CD4 in open-access papers (continued):
Sharing a sentence is not in itself a finding about the gene and the disease.
lupus (continued). "Recent studies on patients with rheumatoid arthritis (RA) and systemic lupus erythematosus echo these results: expansion of CD4+ CD28null cells correlates with significantly higher carotid-intima media thickness and lower brachial artery flow-mediated endothelium-dependent dilation." (PMID 34680058, 2021). "Furthermore, significant up-regulation of miR-148a in patients with SLE and lupus-prone mice compared to healthy controls was found in CD4+T cells." (PMID 33750387, 2021). "Importantly, we show that the JAK inhibitor tofacitinib alleviates lupus through the upregulation of TGFβRI expression to inhibit CD4+ T cell activation." (PMID 34394075, 2021). "In addition to inhibiting immunogenic CD4+ T cell populations, IL-10+ Bregs are also able to convert naïve CD4+ T cells into Tregs and IL-10-secreting type-1 regulatory CD4+ T cells (Tr1), as shown in experimental arthritis, lupus, and EAE." (PMID 33995344, 2021). "In addition, levels of two microRNAs (miR-101 and miR-26a) targeting and regulating EZH2 in CD4+ T cells of lupus patients were negatively correlated with lupus disease activity." (PMID 33679454, 2021). "In the present work, we performed an in-depth analysis of BTLA expression on CD4+ T cell subsets suspected to play a key role in lupus pathogenesis, either by promoting the Ab-response or by limiting lymphocyte activation, i.e. cTFH cells and Tregs respectively." (PMID 34899718, 2021). "CD25 and CD71 (the transferrin receptor), or costimulatory molecules, such as CD154/CD40L (a type II transmembrane protein belonging to the tumor necrosis factor family) are predominantly expressed at the surface of mature, activated lupus CD4+ T cells that proliferate." (PMID 34744730, 2021). "Furthermore, the activity of lupus has also been associated with an increase in TFH cells, a subset of helper CD4 T cells that play a crucial role in the generation of antibodies." (PMID 33763492, 2021). "Interestingly, we have previously shown that BTLA expression is significantly diminished in lupus CD4+ T cells compared to HC following in vitro TCR activation." (PMID 34899718, 2021). "However, the T-B crosstalk, leading to B cell differentiation into plasma cells, represents a central element in lupus pathogenesis, and as such, CD4+ T cells are key contributors of the altered immune response as well." (PMID 34899718, 2021). "We recently demonstrated that the BTLA pathway is altered in CD4+ T cells from lupus patients." (PMID 34899718, 2021). "In addition to reduced DNMTs-mediated passive demethylation, the TETs-mediated active demethylation pathway has been recently implicated in the regulation of the DNA methylation status in lupus CD4+ T cells." (PMID 34062726, 2021). "Moreover, transfection of miRNAs or miRNA inhibitors have beneficial effects on alleviating CD4+T cell disease phenotype, highlighting the important role of miRNAs in lupus-like CD4+T phenotype transformation." (PMID 34408748, 2021). "The increased percentage of human IL-17+ Tfh cells was detected in the spleens of NSG mice (8 weeks old) engrafted with PBMCs (1×107cells/mouse) from patients with active lupus, while this process could be halted by the knockdown of RORγ in human CD4+ T cells." (PMID 35116040, 2021). "T cells from patients with active lupus manifest increasedmitochondrial oxidative phosphorylation and reactive oxygen species (ROS).Oxidative stress of CD4+ T cells results in decreased levels of DNMT1,DNA demethylation, and upregulation in expression of several genes." (PMID 33097564, 2020). "It was also reported that Cluster of Differentiation 4 (CD4+) T cells from a lupus-prone mouse model, as well as from SLE patients, exhibited elevated glycolysis and mitochondrial oxidative metabolism as compared to nonautoimmune controls, both ex vivo and after in vitro activation." (PMID 32899806, 2020).
lupus (continued). "Furthermore, with DC stimulated with ubiquitylated MPO a trend towards increased expression of CD25 and Ki67 was found in lupus CD4+ lymphocytes, while the opposite was documented in controls (p < 0.05)." (PMID 33176801, 2020). "It is noteworthy that our study was performed in vitro with lupus CD4+ T cells." (PMID 32646370, 2020). "Another study showed that naïve CD4+ T cells from lupus patients had impaired production of IL-2." (PMID 33271810, 2020). "Moreover, inhibiting hsa_circ_0012919 corrects the DNA hypomethylation of CD70 and CD11a in lupus CD4+T cells by promoting DNMT1 activity." (PMID 32308657, 2020). "Furthermore, treatment with activated B cells inhibited the percentage of CD4+IL-17+ Th17 cells, decreased intracellular RORγt expression in CD4+ T cells of lupus mice spleens, and reduced serum IL-17." (PMID 32127533, 2020). "We next investigated whether EGR2 mRNA expression was upregulated in purified splenic CD4+ T cells from MRL-lpr mice as well as the other two different murine lupus stains B6.MRL-Faslpr/J (B6-lpr) and B6.NZMSle1/Sle2/Sle3 (B6.sle123) mice at diseased stage." (PMID 32646370, 2020). "To test whether these pathways were also critical for CD138 expression on lupus T cells, we treated CD4+TCRβ+CD138- cells with rapamycin, a specific mTOR inhibitor, and assessed the increase in CD138 expression." (PMID 32849532, 2020). "The malfunction of CD4+ Tregs is associated with autoimmune responses such as rheumatoid arthritis (RA), multiple sclerosis (MS), type 1 diabetes (T1D), inflammatory bowel diseases (IBD), psoriasis, systemic lupus erythematosus (SLE), and transplant rejection." (PMID 32235291, 2020). "Unexpectedly, the deletion of Mir223 exacerbated the lupus phenotypes associated with increased population of S1PR1+CD4+ T in spleen and the enhanced infiltration of S1PR1+CD4+ T cells in inflamed kidney tissues, suggesting compensatory role of Mir223 in the pathogenesis of lupus nephritis." (PMID 33574820, 2020). "Also, inhibition of mTOR is shown to reduce the production of dnT cells and favors the expansion of therapeutic CD4+CD25+Foxp3+ Treg cells in lupus-prone mice and SLE patients." (PMID 32849532, 2020). "The increase of EGR2 in lupus T cells might be a consequence of an inflammatory milieu with heightened T cell activation (CD44+CD4+) following lupus development." (PMID 32646370, 2020). "For instance, CD4 + T cells in Lupus patients show epigenetic changes in the insulin pathway." (PMID 33298174, 2020). "To characterize the disease kinetics of lupus development, we scored NZBxW mice according to their age and proteinuria, determined their auto-antibody concentrations and analyzed the expression of PD-1 and four main cytokines in CD4+ Tmem cells." (PMID 32441253, 2020). "In addition, the in vitro stimulation of TLR2 on CD4+ T cells from patients with systemic lupus erythematosus increased cytokine production." (PMID 32079183, 2020). "Indeed, the top motifs identified for ac4C peaks, “CRGRA” and “CCRCCRC,” in lupus CD4+ T cells provide potential targets that differ from those in HCs." (PMID 32984334, 2020). "The increase of EGR2 in CD4+ T cells may reflect the higher rate of activated CD4+ T cells (CD44+CD4+) in lupus mice." (PMID 32646370, 2020). "Interestingly, Human Parvovirus B19 specific GzmB producing CD4+ T cells may contribute to RA and systemic lupus erythematosus (SLE) associated with chronic B19 infection." (PMID 32226027, 2020). "Furthermore, NB-DNJ treatment restores the functionality of B and T lymphocyte attenuator (BTLA), an inhibitory receptor, similar to CTLA-4 and PD-1, in lupus CD4+ T cells." (PMID 32257420, 2020). "Moreover, we demonstrated the ac4C-modified regulatory network of gene biological functions in lupus CD4+ T cells." (PMID 32984334, 2020).
lupus (continued). "We performed RT-qPCR analysis and found a significant increase of EGR2 mRNA expression in human lupus PBMCs and in CD4+ T cells from three different murine lupus models including MRL-lpr, B6-lpr, and B6.sle123 mice at diseased stage when compared to age-matched control MRL or B6 mice." (PMID 32646370, 2020). "CircIBTK serves as the miR-29b sponge, which may inhibit the activation of the AKT signaling pathway in lupus CD4+ T cells by sponging miR-29a." (PMID 32308657, 2020). "EZH2 is overexpressed in CD4+ T cells from patients with systemic lupus erythematosus (SLE)." (PMID 32395334, 2020). "PCG may alleviate nephritis in lupus-prone mice by rebalancing the population of splenic CD4+ T cells, particularly by increasing the population of Treg cells secreting both IL-10 and TGF-β1." (PMID 32674502, 2020). "Increased CD70+ CD4+ T lymphocytes were also observed in systemic lupus erythematosus (SLE) and rheumatoid arthritis (RA) patients, further confirming the hypothesis." (PMID 32559178, 2020). "Besides, in lupus CD4+ T cells, 5-hmC binds in transcriptional regulatory regions of lineage-specific signature genes, such as IL-17 and IFN-gamma, which promote inflammation." (PMID 31611879, 2019). "These highly cytotoxic CD4 T cells were isolated from disease-affected tissues in patients with rheumatoid arthritis, systemic lupus erythematosus, multiple sclerosis, or other chronic inflammatory diseases and their numbers appeared to be linked to disease severity." (PMID 30984377, 2019). "A substantial component of systemic autoimmune disease such as lupus involves the breakdown of lymphocyte tolerance, primarily through the expansion of autoreactive CD4+ T cells that provide help to B cells, which can in turn produce autoantibodies with various specificities." (PMID 31356154, 2019). "Likewise, treatment with UVB or 5-aza-deoxycytidine induces increased HERV-E mRNA expression in CD4+ T cells from patients with systemic lupus erythematosus (SLE)." (PMID 31801288, 2019). "RFX1 downregulation caused CD11a, CD70, and IL17A overexpression by reducing DNA methylation and increasing H3 acetylation levels in the promoter region of CD11a, CD70, and IL17A in the CD4+ T cells of systemic lupus erythematosus (SLE) patients, which contributed to autoimmune responses." (PMID 30857550, 2019). "Interestingly, reduced GRAIL and Cbl-b levels have been reported in CD4+ T cells from lupus patients, a defect that correlated with reduced numbers of Tregs in periphery." (PMID 31824482, 2019). "Abnormal histone modification patterns have been reported in the CD4+ T cells of lupus patients." (PMID 31001259, 2019). "RFX1 downregulation causes CD11a, CD70 and IL17A overexpression by reducing DNA methylation and increasing H3 acetylation levels in the promoter region of CD11a, CD70 and IL17A in the CD4+ T cells of systemic lupus erythematosus (SLE) patients, which contributes to autoimmune responses." (PMID 31737059, 2019). "However, there are no published reports describing careful identification and subset characterization of brain infiltrating CD4+ T cells in murine lupus." (PMID 29593732, 2018). "The reduction in CD3+CD4+/CD3+CD8+ ratio was usually associated with malignancies or the attack of the virus such as HIV infection, and the reduction also existed in the mouse model of systemic lupus erythematosus." (PMID 29483932, 2018). "The importance of IRF5 for lupus pathogenesis was also demonstrated by the attenuation of the disease in mouse models deficient of IRF5, which was accompanied with decreased activated CD4+ T cells and autoantibodies." (PMID 30061896, 2018). "In addition, eighteen X-linked miRNAs were shown to be overexpressed in CD4+ T cells of women with lupus, five of those—in experimentally demethylated CD4+ T cells suggesting that demethylation contributed to the escape of Xi." (PMID 30455694, 2018).
lupus (continued). "Furthermore, miRNA-148a can contribute to DNA hypomethylation in lupus CD4+ T cells by repressing DNA methyltransferase 1 expression." (PMID 30036399, 2018). "Here we show reduced expression of the transcription factor RFX1 in CD4+ T cells from patients with systemic lupus erythematosus, which leads to IL-17A overexpression through increased histone H3 acetylation and decreased DNA methylation and H3K9 tri-methylation." (PMID 29422534, 2018). "Autoreactive MZ B cells enter follicles and interact with CD4+ T cells in lupus-prone mice." (PMID 29382365, 2018). "Additionally, EZH2 is highly expressed in naïve CD4+ T cells in lupus patients compared to healthy controls and positively correlates with lupus disease activity." (PMID 30545086, 2018). "The dramatic response of lupus TFH cells to 2DG while reducing the frequency of TEM cells requires the combination of 2DG and metformin (21 and this study) indicate that lupus TFH cells have a greater glucose requirement than other activated effector CD4+ T cells." (PMID 30348969, 2018). "Moreover, high levels of miR-21, miR-148a, and miR-29b were shown to positively correlate with DNA hypomethylation in lupus CD4+ T cells, and suppression of these miRs is beneficial." (PMID 29854836, 2018). "For example, compared with that in healthy individuals, the expression of miRNA miR-21 is elevated in CD4+ T cells from lupus patients; overexpression of miR-21 suppressed the expression of PDCD4, a selective protein translation inhibitor, and regulated aberrant T cell responses." (PMID 30577810, 2018). "Based on therapeutic effects of the combination of metformin and 2DG in lupus mouse models that normalized the expansion of effector CD4+ T cells, we hypothesized that these metabolic inhibitors would also have a beneficial effect in autoimmune arthritis." (PMID 30233578, 2018). "In a previous study, CD154 levels increased in CD4+ T cells from pediatric lupus patients." (PMID 28793932, 2017). "CD4+ T cells were isolated from the blood of lupus patients." (PMID 28793932, 2017). "CX3CR1- and CD103-expressing cells are primarily APC that can capture bacteria from the gut lumen and transport them to the MLN, where they present antigens and activate CD4+ T cells to produce IL-6 that suppresses Treg, which is vital to lupus pathogenesis in lpr mice." (PMID 28697806, 2017). "Apoptotic CD4+ T cells from patients with rheumatoid arthritis and systemic lupus erythematosus were demethylated compared to healthy controls and favoured production of IL-6 when cultured with healthy macrophages, in contrast to the TGFβ produced in response to healthy AC." (PMID 28169339, 2017). "However, the proportion of SLAMF6-expressing CD4 T cells was higher in the active lupus patients compared with the patients in remission." (PMID 28387859, 2017). "In this review, we will discuss recent findings implicating extracellular vesicles (EVs) at different steps of CD4+ T cell differentiation to specific effectors, with a focus on the Th17/Treg balance and its alterations in systemic lupus erythematosus and multiple sclerosis." (PMID 28157168, 2017). "Additionally, studies have found that methylation status at certain genes in lupus CD4+ T cells can be removed by growth arrest and DNA damage-induced 45alpha (Gadd45a)." (PMID 28785369, 2017). "Conversely, the anti-inflammation cells CD4+Foxp3+ Treg cells were significantly lower in B7-H4-KO BMDCs-induced lupus mice compared to control mice; thus, these results show that the lack of B7-H4 on DCs has changed the balance between T effector and Treg cells in this model." (PMID 29321778, 2017). "We examined the components of the inflammatory cells in the lupus mice and found that the percentages of CD4+ T, IL-2+, IL-17+ cells in peripheral blood were significantly higher in B7-H4-KO BMDCs-ALD-DNA induced lupus mice than that in WT BMDCs-ALD-DNA induced lupus mice." (PMID 29321778, 2017).
lupus (continued). "Altogether, these results suggest that thymic B-cell reduction may initiate the thymic CD4 or CD8 lineage ‘decision’ in lupus-prone and pristane-treated mice." (PMID 29163765, 2017). "ELISA assay showed marked increase of perforin and granzyme B derived from the NKG2D+CD4+ T cells co-cultured with lupus serum that stimulated Treg cells, indicating that NKG2D+CD4+ T cells could kill target cells by secreting cytotoxic mediators in vitro." (PMID 28455530, 2017). "However, stimulation with SEB demonstrated differences in the CD4+ Teff as well as Tnaïve/mem populations between the HC, inactive, and active lupus patient." (PMID 28555177, 2017). "It has been suggested that CD4+ T cells play prominent roles in the pathogenesis of lupus." (PMID 29321778, 2017). "Some authors suggest that a defect in DNMT1 may be the primary reason of abnormal DNA methylation in CD4+ T cells from lupus patients." (PMID 28349196, 2017). "Interestingly, in lupus CD4+ T cells, it has been shown that miR-29b inhibits DNMT1 by indirectly binding to Sp1 which is a permissive regulator of DNMT1." (PMID 28785369, 2017). "Thus altogether, as with lupus B cells, lupus monocytes unlikely provide NKG2DL driving NKG2D+CD4 T cell proliferation." (PMID 28944101, 2017). "Unexpectedly, we found that CD4+CD8+T cells were reduced in lupus-prone mice." (PMID 29163765, 2017). "CD4+ T cell DNA methylation is impaired in patients with active lupus." (PMID 28239687, 2016). "The genes encoding perforin (PRF1), CD11a (ITGAL), CD70 (TNFSF7), CD40L (CD40LG), and the killer cell immunoglobulin-like receptor (KIR) genes are normally suppressed by DNA methylation in CD4+ T cells, but are demethylated and over-expressed by CD4+ T cells from patients with active lupus." (PMID 28239687, 2016). "Furthermore, CD4+ T cells from female lupus patients, which overexpressed CD40L mRNA, were able to promote autologous B cell stimulation and autoAb production." (PMID 27635407, 2016). "CD4+CD28− stress-induced, PP5 overexpressing T cells have decreased ERK and JNK pathway signaling, low Dnmt1 levels, and overexpress methylation sensitive genes including KIR2DL4, CD70 and perforin, similar to the epigenetically altered CD4+CD28+ T cells from patients with active lupus." (PMID 28239687, 2016). "We tested if PP5 is increased in CD4+CD28+ T cells by oxidative stress, if PP5 transfection causes overexpression of methylation sensitive genes in T cells, and if PP5 is overexpressed in lupus T cells." (PMID 28239687, 2016). "Furthermore, the percentages of CD4+ T cells producing IL-21 are significantly enhanced in lupus patients." (PMID 27635407, 2016). "Dnmt1 levels, as well as ERK pathway signaling are decreased in CD4+ T cells from lupus patients." (PMID 28239687, 2016). "Similarly, CD4+ T cells from women with active lupus overexpress CD40L but CD4+ T cells from men with active lupus do not." (PMID 28239687, 2016). "Increased miR-21, miR-148a, and miR-126 in lupus CD4+ T cells reduced the expression of DNMT1 directly or indirectly, leading to DNA hypomethylation and overexpression of autoimmune-associated methylation-sensitive genes such as CD70, lymphocyte function-associated antigen 1 (LFA-1), and CD11a." (PMID 27070142, 2016). "PP5 expression is increased in CD4+CD28+ T cells from lupus patients." (PMID 28239687, 2016). "In addition, the gene expression of sh2d1a, map3k1, spn and stat5b was enhanced after NaCl treatment, consistent with the findings in lupus CD4+T cells." (PMID 27325182, 2016). "The recent genome-wide DNA methylation profiling studies revealed a persistent hypomethylation of Type I interferon-related genes in CD4+ T cells, suggesting an involvement of epigenetic mechanisms in heightened type I interferon signaling and sensitivity in lupus T cells." (PMID 27070142, 2016).